KRTAP20-2 (keratin associated protein 20-2)
Description:
In the hair cortex, hair keratin intermediate filaments are embedded in an interfilamentous matrix, consisting of hair keratin-associated proteins (KRTAP), which are essential for the formation of a rigid and resistant hair shaft through their extensive disulfide bond cross-linking with abundant cysteine residues of hair keratins. The matrix proteins include the high-sulfur and high-glycine-tyrosine keratins.
Synonyms: KAP20.2
Tractability: No criterion of Open Targets' tractability assessment is met for any kind of drug.
Gene: Protein-coding gene on chromosome 21 (30,635,206 to 30,635,619, forward strand). Ensembl gene ENSG00000184032.
Pathways (Reactome):
Developmental Biology: Keratinization
Gene Ontology:
Cellular component: cytosol
Genetic constraint (gnomAD): Loss-of-function variants: 7 observed, 5.45 expected, observed/expected ratio (o/e) 1.28, 90% interval 0.7 to 1.89. That is too few expected variants to judge how well the gene tolerates losing a copy. Missense variants: 59 observed, 60.1 expected, observed/expected ratio (o/e) 0.98, 90% interval 0.8 to 1.22. Synonymous variants: 18 observed, 24.1 expected, observed/expected ratio (o/e) 0.75, 90% interval 0.51 to 1.11.
Homologues: Orthologues: chimpanzee KRTAP20-2 (95% identical), pig KRTAP20-2 (71% identical).